ZNF843 (zinc finger protein 843)
Synonyms: MGC46336
Tractability: No criterion of Open Targets' tractability assessment is met for any kind of drug.
Gene: Protein-coding gene on chromosome 16 (31,432,593 to 31,444,323, reverse strand). Ensembl gene ENSG00000176723.
Subcellular location (Human Protein Atlas): Nucleoplasm; Nuclear speckles
Gene Ontology:
Molecular function: protein binding; sequence-specific double-stranded DNA binding
Genetic constraint (gnomAD): Loss-of-function variants: 1 observed, 0.92 expected, observed/expected ratio (o/e) 1.09, 90% interval 0.28 to 1.9. That is too few expected variants to judge how well the gene tolerates losing a copy. Missense variants: 482 observed, 448.21 expected, observed/expected ratio (o/e) 1.08, 90% interval 1 to 1.16. Synonymous variants: 185 observed, 194.95 expected, observed/expected ratio (o/e) 0.95, 90% interval 0.84 to 1.07.
Homologues: Orthologues: chimpanzee ZNF843 (93% identical).